MMP2 (matrix metallopeptidase 2)
Diseases named in the same sentence as MMP2 in open-access papers (continued):
Sharing a sentence is not in itself a finding about the gene and the disease.
tumor (continued). "More importantly, after silencing LNMAT1 expression in MM cells with shRNAs (P < 0.05), the mRNA expression levels of MMP-2, MMP-9, and N-cadherin, which are markers of tumor invasion-metastasis cascade, were found to be downregulated by qRT-PCR." (PMID 31334110, 2019). "MMP2 and MMP9 were members of metal matrix protease family, which was closely related to tumor migration." (PMID 31384174, 2019). "Gelatinase A (MMP-2) is the most abundant MMP in the tumor stroma and contributes to tumor invasion." (PMID 31510956, 2019). "The protein expression levels of the tumor invasion and migration-related proteins matrix metalloproteinase 9 (MMP9) and MMP2 were also reduced by Akt inhibition." (PMID 30850586, 2019). "We focused our studies in MMP-2 and MMP-9 because they are related to invasive and metastatic processes, and a highly invasive capacity of tumor cells." (PMID 31671408, 2019). "This suggests that LOX can upregulate the expression and enzyme activity of MMP-2 and MMP-9, which verified our results in human tumor tissues." (PMID 31777578, 2019). "All non-tumoral breast tissues showed low expression/activity of both ENO1 and MMP-2 and MMP-9, whereas higher expression/activity was observed in the paired tumour samples." (PMID 31416219, 2019). "In order to confirm the relationship between LOX and MMP-2 and MMP-9 in tumorigenesis and tumor progression, we studied LOX, MMP-2, and MMP-9 in human tumor tissues, animal models, and in vitro cell culture." (PMID 31777578, 2019). "Increased MMP (e.g., MMP-2, MMP-7 and MMP-9) expression occurs frequently upon Wnt stimulation of tumour cell invasion." (PMID 31718047, 2019). "Mechanistically, SHMT1 acted as a tumor suppressor by targeting NOX1 and subsequently restrained ROS production, EMT and MMP2 expression in HCC cells." (PMID 30755243, 2019). "MMP-2 (gelatinase A) is one of the MMP subgroups that selectively degrade type IV collagen and it plays a key role in tumor invasion, metastasis, and angiogenesis." (PMID 31660294, 2019). "In tumor cells, MSE is positively correlated with HIF1α, MMP2 and MMP9 expression and thus can reflect the status of the tumor microenvironment." (PMID 31266540, 2019). "It directly targets VEGF-A, inhibiting tumor progression and angiogenesis by regulating the VEGF-A/MMP-2 signaling." (PMID 31757094, 2019). "TGF-β has been reported to contribute to tumor progression by inducing epithelial-to-mesenchymal transition, cell migration and invasion of epithelial tumor cells through stimulating MMP-2 and MMP-9 secretion into the tumor microenvironment." (PMID 31568519, 2019). "Downstream targets of STAT3, among which matrix metalloproteinase 2 (MMP2) is also differentially modulated in the tumor biopsies." (PMID 30645971, 2019). "Since matrix metalloproteinases (MMPs) promote tumor metastasis by degrading the extracellular matrix (ECM), western blotting and gelatin zymography were used to measure the relative amounts of MMP-2 or MMP-9." (PMID 31531187, 2019). "In order to evaluate the mechanism underlying their inhibitory action on migration and invasion, we measured the activities of MMP-2 and MMP-9 involved in tumor cell migration and invasion by gelatin zymography." (PMID 31109130, 2019). "Some members of the MMP family, especially MMP-2 and MMP-9, known as gelatinases A and B, are critically involved in tumor invasion, and metastasis and their expression have been associated with poor overall survival in patients with gastric cancer." (PMID 31817563, 2019). "We found that the expression and enzyme activity levels of MMP-2 and MMP-9 were decreased in mouse tumor tissues after LOX inhibition." (PMID 31777578, 2019). "After LOX inhibition, we analyzed the effects on protein expression and enzyme activity of MMP-2 and MMP-9 in tumor tissues from the nude mouse model." (PMID 31777578, 2019).
tumor (continued). "In NB, it has been demonstrated that under hypoxic conditions, TLX can activate both MMP-2 and OCT-4 genes, stimulating self-renewal of tumor-spheres and promoting migratory abilities of NB cells." (PMID 31191243, 2019). "Under hypoxic conditions, TLX activates both MMP-2 and OCT-4 genes, stimulating tumor-sphere self-renewal and promoting migratory abilities of NB cells." (PMID 31191243, 2019). "The mechanism whereby MMP-2 and MMP-9 activity induces cancer angiogenesis involves the cleavage of latent TGF-β in a CD44-dependent manner, which can promote tumor growth and invasion." (PMID 31921634, 2019). "The expression levels of some key tumor metastasis-related proteins including phospho-AKT, vimentin, cofilin, and MMP-2 decreased in MBNL2 overexpressed cells." (PMID 31320607, 2019). "The observed strong downregulation of TIMP3 and disturbed MMP2/TIMP3 expression ratio can be explained as crucial activities in the ECM remodeling process, enabling creation of a microenvironment conducive to tumor growth." (PMID 31921636, 2019). "Western blot data showed that the protein levels of PCNA, CDK4, CDK6, Cyclin D1, MMP-2, MMP-9, and Bcl-2 were decreased, but cleaved caspase-3 was increased in tumor tissues of ApoE KO mice compared to those of WT mice." (PMID 31275318, 2019). "First, we used the Repository of Molecular Brain Neoplasia Data (REMBRANDT) dataset to compare mRNA expression of MMP-2 and MMP-9 in non-tumor control and GBM samples." (PMID 31590360, 2019). "In summary, during tumor invasion and metastasis, MMP-2 and MMP-9 are used to degrade the ECM and basement membrane so that tumor cells can detach, invade, and metastasize." (PMID 31777578, 2019). "Among MMPs, MMP-2 and MMP-9 are two important enzymes, which are involved in the remodeling of extracellular matrix and are key mediators of invasion, metastasis, and tumor angiogenesis and facilitate VM formation." (PMID 30723742, 2019). "MMP-2 and MMP-9 can degrade type IV collagen in the basement membrane and facilitate tumor cell metastasis." (PMID 31781485, 2019). "The western blot assay and immunohistochemistry studies showed that the expression of MMP9, MMP2, VEGF and STAT3 in tumor and liver tissues were significantly decreased in a dose-dependent manner." (PMID 30651572, 2019). "YFTL significantly reduced MMP-2, MMP-9, N-cadherin and Vimentin expression, but markedly increased E-cadherin expression in the tumor and lung tissues of tumor-bearing mice compared with the MC group." (PMID 30781674, 2019). "Specifically, among MMPs, MMP-2 and MMP-9 are most closely related to the invasion and metastasis of tumor cells." (PMID 31569766, 2019). "MMP-14 activates both MMP-2 and MMP-13, in the presence of TIMP-2, with a demonstrated effect in tumor invasion and metastasis, by promoting cell migration." (PMID 31886121, 2019). "Nanoparticles composed of poly(D, L-lactic-co-glycolic acid)-block-polyethylene glycol copolymer, blended with a tumor-activated prodrug, composed of an MMP2-sensitive peptide conjugating DOX to PLGA, released higher amounts of DOX when incubated with MMP2." (PMID 31370252, 2019). "In other studies, plasma levels of LCN2/matrix metallopeptidase 9 complex, MMP2, TIMP1, TIMP2 and TIMP3 were correlated to tumor size, lymph node involvement, tumor differentiation and prediction of tumor stage and T status in patients affected with HNSCC." (PMID 31014274, 2019). "MMP-2 and MMP-9 expression is elevated in malignant tumors and largely contribute to the ability of tumor cells to metastasize, as they degrade collagen type IV, which is the main component of the basement membrane." (PMID 31554180, 2019). "Third, MMPs, especially MMP2 and MMP9, that degrade constituents of the extracellular matrix to disrupt the physiological barrier were found to participate in tumour metastasis." (PMID 31423109, 2019).
tumor (continued). "In the context of tumor invasion, TIMP-2 is expected to serve as an anti-invasive/anti-metastatic agent through inhibition of MMP-2." (PMID 31088428, 2019). "C26 cells stimulation by either sICAM-1 administration or co-culture with LSECs results in tumor cell secretion of inflammatory PGE2 and IL-6, VEGF, uPA, MMP-2, MMP-9." (PMID 31511625, 2019). "The effective regulation by SPG-56 of the expression of metastasis-related proteins MMP2, MMP9, VEGF, Occludin, Claudin and STAT3 further confirmed the inhibition by SPG-56 of tumor metastasis." (PMID 30651572, 2019). "The tumor specificity of Cltx was previously attributed to the distinct targets; CLC-3, MMP2 and annexinA2, and while all 3 are likely involved in aspects of Cltx function, none fully accounts for its multiple diverse activities." (PMID 31208428, 2019). "The mechanism by which tumor cells activate platelets to form TCIPA includes the stimulation of the release of various molecules, such as ADP, MMP-2 and PGE2, and generation of thromboxane A2 (TXA2)." (PMID 30927923, 2019). "Matrix metalloproteinase-2 (MMP-2), a member of the MMPs family, is involved in the breakdown of extracellular matrices, a process promoting tumor invasion." (PMID 31337431, 2019). "Increased activation of MMP2 and MMP9 is mediated by the levels of IL-8, which can promote the invasive capability of a tumor." (PMID 30664713, 2019). "Marsdenia tenacissima inhibits tumor growth via the modulation of VEGF, MMP-2, MMP-9, GSH-Px, SOD, CAT, and MDA." (PMID 31341493, 2019). "Zymography elucidated the proteolytic activity of both MMP-9 and MMP-2 (both active and short molecular forms) in GZ17-6.02 treated mice as compared to control mice in the primary tumor and metastatic organs." (PMID 30899425, 2019). "The relationship between LOX and MMP-2 and MMP-9 in tumorigenesis and tumor progression are still unclear." (PMID 31777578, 2019). "Matrix metalloproteinase-2 (MMP-2) and the imbalance between MMP-2 and its tissue inhibitor (TIMP-2) play a critical role in tumor progression." (PMID 30719232, 2019). "Activity of MMPs, such as MMP-2 and MMP-9, is essential for the degradation of extracellular matrix (ECM), which results in the migration and invasion of tumor cells." (PMID 31391858, 2019). "On the other hand, it has been validated that an imbalance between MMP-2, which regulates ECM degradation, and TIMP-1, its tissue inhibitor, plays an important role in tumour invasion and cancer metastasis." (PMID 31836811, 2019). "It was concluded that the increase in MMP-2, TIMP-1 in tumor, and MMP-9 in stroma were characterized by a decrease in the odds ratio for 5-year survival." (PMID 31223594, 2019). "Our data showed that the expression of MMP-9 and MMP-2 was altered by DANCR/miR-135a-5p/KLF8 axis, which just further proved the regulatory network on tumor malignancies from the point of molecular level." (PMID 31827393, 2019). "MMP-2 and MMP-9 are the most important factors in the MMP family in promoting tumor invasion and metastasis." (PMID 30622441, 2019). "MMP-2 and MMP-9 levels have been reported in correlation with local invasion, cervical nodal metastasis, tumor progression and prognosis of HNSCC patients." (PMID 30927923, 2019). "MMP2, a member of the MMP family, can recognize various extracellular matrix components as substrates to enhance aberrant tumour angiogenesis and metastasis." (PMID 30947736, 2019). "MMPs, especially MMP2 and MMP9, are known to take an important part in tumor growth, migration and invasion through degradation of extracellular matrix (ECM) and activation of growth factors." (PMID 31007650, 2019). "Western blotting was used to quantitate the relative expression levels of MMP-2 and MMP-9 in mouse tumor tissues, and gelatin zymography was used to quantitate their enzyme activity levels." (PMID 31777578, 2019). "At molecular level, the expression of MMP-2 and MMP-9 in tumor tissues was also reduced by DANCR inhibition." (PMID 31827393, 2019).
tumor (continued). "It has been revealed that MMP2 and MMP9 are involved in regulating tumor cell migration and invasion." (PMID 31007650, 2019). "Western blotting represent relative level of MMP2 and VEGF protein in the tumor tissue from each C57BL/6N stock." (PMID 32257905, 2019). "Functional assays further confirmed that SHMT1 exerted tumor suppressive roles in HCC by inhibiting cell metastasis, EMT and MMP2 expression." (PMID 30755243, 2019). "All these findings suggest that MMP2, MMP9, VEGF, and IL8 are critical during HOXB7-promoted angiogenesis, which in turn supports tumor growth and metastasis." (PMID 30664713, 2019). "MMP-2 and MMP-9 are matrix metalloproteases expressed in tumor cells, which degrade the extracellular matrix (ECM) type IV collagen of the basement membrane during cancer invasion and metastasis." (PMID 31293975, 2019). "Results showed efficient uptake by HT-1080 human fibrosarcoma cells, as PEG prolongs the blood circulation and facilitates the cleavage of MMP-2 by substrate, due to over-expression of MMP-2 in tumor." (PMID 30647857, 2018). "Functionally, COMP/CD36 signaling caused phosphorylation of ERK and AKT, resulting in the upregulation of tumor-progressive genes such as EMT markers, MMP-2/9, Slug and Twist in HCC cells." (PMID 30231922, 2018). "TAMs induce EMT of tumor cells by secreting factors such as interleukelin-6 (IL-6), interleukelin-8 (IL-8), tumor necrosis factorα (TNFα), TGFβ, EGF, VEGF, matrix metalloproteinase-2 (MMP-2) and MMP-9." (PMID 30157906, 2018). "In this study, we found C1q significantly enhanced these expressions, and in-line with these results, it was found in a previous study that the expressional up-regulations of MMP2 and 9 modulate EMT and promote tumor cell migration and invasion." (PMID 29559654, 2018). "Once the conjugate enters tumor cells, the PEG layer is detached from PAMAM by cleavage of MMP-2 sensitive peptide by the action of MMP-2." (PMID 30155269, 2018). "The decrease in MMP‐2 induced by MYOF depletion then affects cell migration and severely suppresses cell invasion, which are required for VM formation by tumour cells." (PMID 29164766, 2018). "Extracellular matrix degradation is an indispensable step in tumor metastasis and invasion, which is mainly mediated by the balance between selected MMPs, such as MMP9 and MMP2." (PMID 30453504, 2018). "Furthermore, the agent-inhibited MMP-2 could lead to the suppression of tumor metastasis." (PMID 30104528, 2018). "Matrix metalloproteinase-2 (MMP-2) and metalloproteinase-9 (MMP-9) degrade structural proteins of invaded tissues and play a crucial role in metastasis of tumor cells and angiogenesis." (PMID 29337896, 2018). "In this process, matrix metalloproteinases (MMP), especially MMP-2 and MMP-9, are crucial for extracellular matrix remodeling and, consequently, the tumor invasiveness." (PMID 29867502, 2018). "Herein, we propose a novel intelligent DDS for microenvironment-responsive tumour targeting and controlled release based on the MEND strategy, MMP-2-triggered degradation of gelatin and hyaluronidases (Hyal)-catalysed degradation of hyaluronic acid (HA)." (PMID 29410811, 2018). "In the present study, increased MMP-24 shed and MMP-2 activation was observed in SNCG-treated tumor cells, suggesting that SNCG was an upstream regulator of MMP-24 and MMP-2." (PMID 29903032, 2018). "We also monitored the expression level of tumor cell-secreted LOX, MMP-2 and VEGFA, and the bone marrow-derived CD11b+ cell number in the distant organs in the in vivo model." (PMID 29848296, 2018). "Both MMP2 and MMP9 have been reported to function in tumor cell invasion, thus leading to metastasis." (PMID 30587839, 2018). "The authors investigated the effect of ECM components on MMP-2 and MMP-9, because they are the key effectors that are involved in the degradation of the basement membrane, an important step during tumor invasion." (PMID 30301152, 2018).
tumor (continued). "The activity levels of pro-MMP-2, MMP-2, pro-MMP-9, and MMP-9 in tumor tissues were compared with the corresponding activities of the adjacent non-tumoral tissues when positive for lytic activity." (PMID 30060564, 2018). "Among the members of the MMPs family, gelatinases MMP-2 and MMP-9 are considered to be the essential regulators of the tumor microenvironment." (PMID 30581847, 2018). "The results of this study showed significant decrease in expression of VEGF, MMP2, MMP9, and CD31 factors in tumor-bearing mice under treatment with umbelliprenin compared to normal saline group." (PMID 30127820, 2018). "Functional analyses revealed that PLOD3 interacts with STAT3, thereby expressing matrix metalloproteinases (MMP-2 and MMP-9) and with urokinase plasminogen activator (uPA) to enhance tumor metastasis." (PMID 30442941, 2018). "Our data show significantly upregulated levels of MMP-1, MMP2, MMP3 and MMP9 mRNA in ESCC tumor tissues compared to the adjacent normal tissues." (PMID 30241395, 2018). "Matrix metalloproteinases MMP2 and MMP9 are involved in tumor invasion, and their protein levels were significantly downregulated at 72 h post-miRNA-agomir transfection." (PMID 29849932, 2018). "We also detected the proliferation-related molecules (Ki67 and PCNA) and the metastatic-related markers (MMP2 and MMP9) in the xenograft tumor tissues by Immunohistochemical staining." (PMID 30333480, 2018). "For instance, reactive astrocytosis as a result of surgical resection can promote tumor cell invasion via the secretion of distinct paracrine factors (e.g. TGF-α, CXCL12, S1P, GDNF, MMP-2, MMP-9)." (PMID 29728948, 2018). "Inhibition of the activity of MMP-2 and MMP-9 in tumour cells can inhibit the effects of cancer cells." (PMID 29751513, 2018). "Tumours in the TP53INP1‐silenced group expressed more Snail, VE‐cadherin, MMP2 and HIF‐1α protein than the control group tumours." (PMID 29655255, 2018). "In our opinion, this is the first comprehensive description of potential activities where MMP-2 and MMP-9 can be involved in the complicated scenario in which the mechanisms of tumor progression are correlated with unfavorable prognosis." (PMID 30060564, 2018). "Secretion of active MMP2 and MMP9 into the stroma of primary tumors allows for break-down of the surrounding tumor matrix and matrix remodeling to promote epithelial cell invasion." (PMID 30458886, 2018). "Matrix metalloproteinase-2 (MMP-2) is an extracellular matrix degrading enzyme, which plays an important role in tumor invasion and is highly expressed in related cancer cells." (PMID 29495404, 2018). "Establishment of such a niche promoted tumor invasion at peritoneal surfaces, mainly through fibroblast release of HGF and matrix metalloproteinase 2 (MMP2)." (PMID 28929459, 2018). "In particular, MMP-2 and MMP-9, which selectively degrade type IV collagen, have been shown to facilitate tumor invasion and metastasis in various cancers." (PMID 29977159, 2018). "Excessive M2 macrophages release MMP2 and MMP9 that can specifically degrade the extracellular matrix, thereby promoting the migration of tumor cells and tumor stromal cells." (PMID 29329591, 2018). "CXCL8 exerts its angiogenic activity by up-regulating matrix metalloproteinase (MMP-2) and MMP-9 enzymes in tumor and endothelial cells leading to degradation of extracellular matrix which is one of pre-requisites for EC migration and organization." (PMID 30344239, 2018). "ECM metalloproteinases (MMPs), especially MMP-2 and MMP-9, cleave ECM components, degrade the basement membrane, and allow tumor cells to penetrate the adjacent matrix stroma." (PMID 29770331, 2018). "The expressions of vascular endothelial growth factor (VEGF), matrix metalloproteinase (MMP)‐2, and MMP‐9, which served as tumor promoter, were detected by Western blot." (PMID 30280514, 2018).